PRMT5 (protein arginine methyltransferase 5)
Diseases named in the same sentence as PRMT5 in open-access papers (continued):
Sharing a sentence is not in itself a finding about the gene and the disease.
cancer (continued). "The deficiency of MTAP results in impaired PRMT5 activity and thus sensitizes cancer cells to GSK3368715." (PMID 36572880, 2022). "Although PRMT5 has been implicated in spliceosome regulation in other cancers, we provide evidence that intact PRMT5 function is also important for spliceosome function in MM." (PMID 35757005, 2022). "It has been known that PRMT5 acts as oncogene to promote cell proliferation and invasion and is associated with worse survival in cancer patients." (PMID 35766227, 2022). "Collectively, our results suggest that PRMT5 inhibition augments anti-AKT or other downstream targeted therapeutics in high-risk metastatic cancers." (PMID 35803962, 2022). "Protein arginine methyltransferase 5 (PRMT5) activity is dysregulated in many aggressive cancers and its enhanced levels are associated with increased tumour growth and survival." (PMID 33462997, 2021). "Numerous reports demonstrate that high protein arginine methyltransferase 5 (PRMT5) expression is associated with a worse prognosis across multiple cancer types, including PDAC." (PMID 34680285, 2021). "At present, inhibition of PRMT5 has also become a potential therapy for methionine adenosine phosphorylase (MTAP)-deficient cancers." (PMID 34513846, 2021). "Our results therefore suggest that small molecule-based transcriptional perturbation of PRMT5 can leverage a mutation-selective vulnerability, that is therapeutically tractable, and has relevance to 9p21 deleted cancers including MPM." (PMID 33795785, 2021). "Mtap gene deficiency was shown to impair PRMT5 activity, sensitizing cancer cells to GSK3368715, and inhibition of PRMT5 produced synergistic cancer cell growth inhibition when combined with GSK3368715 in the same study." (PMID 34769221, 2021). "While studies about the mechanisms by which PRMT5 regulates the cell cycle in cancer can be helpful to infer mechanisms in untransformed Th cells, cancer cells harbor multiple mutations impacting cell cycle checkpoints." (PMID 34168658, 2021). "For instance, the recurrent mutation in splicing factors such as SRSF2, U2AF1, ZRSR2, or SF3B1 in myelodysplastic syndrome is associated with a more significant reduction in cancer cell numbers in response to PRMT5 inhibition." (PMID 34680285, 2021). "Elevated levels of PRMT5 are observed in several types of cancers and are associated with poor clinical outcomes, making PRMT5 an important diagnostic marker and/or therapeutic target for cancers." (PMID 33376131, 2021). "PRMT5 methylation of proteins is implicated in control of normal and pathological conditions, among them development, tissue homeostasis and cancer." (PMID 32743345, 2020). "PRMT5 is overexpressed in a variety of cancers, and its activity is associated with cell transformation." (PMID 33060569, 2020). "Previously, we showed that PRMT5 overexpression augmented certain cancer-associated biological functions in CRC cells in an S15 phosphorylation-dependent manner." (PMID 32456215, 2020). "Recent reports indicate that PRMT5 is overexpressed in a variety of human malignant tumors, suggesting that PRMT5 overexpression is an important high-risk factor and determinant of tumor properties." (PMID 32392182, 2020). "PRMT5 expression is upregulated in most cancer types, and in most cases such upregulation is associated with poor patient survival." (PMID 32743345, 2020). "PRMT5 has been regarded as an oncogene and its overexpression has been associated with poor prognosis in various cancers." (PMID 32328070, 2020). "In conclusion, both NF-κB and PRMT5 are individually known to play critical roles in cancer progression, and the mechanisms underlying the cooperativity between the two are inherently critical and complicated." (PMID 32456215, 2020). "This vulnerability can be exploited therapeutically, and PRMT5 targeting in MTAP‐deficient cancers has indeed become the focus of recent research." (PMID 32301278, 2020).
cancer (continued). "High PRMT5 expression in human cancers is implicated in tumor promotion through histone tail modifications that repress miRNAs that target tumor promoting genes." (PMID 32743345, 2020). "The PRMT5 activity has been linked with cell transformation and thus implicated in cancer initiation." (PMID 32932854, 2020). "Gao and his colleagues reported PRMT5 overexpression and mutations found in a broad range of cancers by analyzing the cBioPortal database." (PMID 33375283, 2020). "Knockdown of PRMT5 suppresses cell growth, and overexpression of PRMT5 causes hyperproliferation of cancer cells." (PMID 30675521, 2019). "The Hsl7 human homolog, Prmt5, is linked to cancer through its activity as a transcriptional repressor." (PMID 31403050, 2019). "Several reports have shown that PRMT5 overexpression is associated with hyper-proliferation and apoptosis resistance in cancer cells, and the inhibition of its activity leads to the repression of cancer genes and slows growth." (PMID 30736843, 2019). "As a result, PRMT5 deficiency can either restore the expression of tumor suppressor genes or reduce the transcription of oncogenes to block cancer cell growth." (PMID 30858358, 2019). "Altogether, these results suggest that NAA40 promotes PRMT5 transcriptional activation, which in turn influences the expression of vital cancer-associated genes in CRC cells." (PMID 30858358, 2019). "The results also indicate that in CRC cells NAA40 regulates H4R3me2s levels through transcriptional control of PRMT5, which subsequently modulates the expression of its cancer-associated target genes." (PMID 30858358, 2019). "Regulation of PRMT5 via miR-96/92b has been reported in cancer cells, in which loss of these miRNAs enhances the pool of mRNA available for PRMT5 translation." (PMID 30941147, 2019). "PRMT5 amplifications, deletions and mutations occur with significant frequency in many cancer types, including uterine, head and neck, bladder, ovarian, gastric, and lung." (PMID 29518110, 2018). "Increased PRMT5 levels have been found to correlate with poor prognosis in various cancer, and in a follow up study, the same group further validated the association of PRMT5 with PDCD4." (PMID 30613353, 2018). "Studies over the last decade have clearly shown that enhanced PRMT5 expression in cancer cells is linked with transcriptional silencing of its target tumor suppressor genes." (PMID 30613353, 2018). "We identified FOXP1, a gene which is associated with cancer stem cell function, as dependent on PRMT5 for expression." (PMID 29876520, 2018). "Understanding the adaption of processes to the increased MTA concentration in cancer cells with MTAP deletion may be crucial for understanding the causes of resistance to PRMT5 and MAT2A inhibitor therapies." (PMID 41465382, 2025). "MATP loss of cancer cells leads to the accumulation of its substrate MTA and further inhibits the activity of arginine methyltransferase, which causes the heightened susceptibility to the PRMT5 depletion and impairs the cancer cell viability through synthetic lethality machinery." (PMID 41445748, 2025). "Furthermore, SIRT7 has been shown to mediate the desuccinylation of protein arginine methyltransferase 5 (PRMT5) at K387, which has been linked to the promotion of lipid metabolism and, consequently, cancer cell proliferation, migration, and invasion." (PMID 39781339, 2025). "Since DNA repair pathways are frequently misregulated in cancers, we investigated whether PRMT5 is abnormally regulated in specific cancer types and whether its aberrant regulation is associated with specific genetic abnormalities." (PMID 40091834, 2025).
cancer (continued). "To investigate the association between PRMT5 and DNA damage repair genes across various types of cancer, we analyzed the correlation between the expression levels of PRMT5 and DNA damage repair genes using TIMER2.0 with data from The Cancer Genome Atlas (TCGA)." (PMID 39989968, 2025). "Notably, both enzymes are implicated in chemoresistance, and targeting PRMT1 and PRMT5 has demonstrated therapeutic potential in various cancers." (PMID 40393971, 2025). "Due to these interactions as well as its increased expression in tumor cells, PRMT5 was linked to cancer proliferation, migration, epithelial to mesenchymal transition, invasion, and metastasis and was suggested as potential therapeutic anti-cancer target." (PMID 38417630, 2024). "Notably, PRMT5 has been implicated in cancer development and immuno-oncology, where it affects the anti-tumor function of PD-L1 by regulating its expression." (PMID 39366935, 2024). "Furthermore, PRMT5 has been associated with the regulation of cell cycle and immune cell invasion in the context of cancer, which intersect with the lower ranked cloperastine-ADPKD pathways described here." (PMID 38846086, 2024). "Co-opting of PRMT5 and spliceosomal regulation has been shown to be essential for lymphomagenesis in an Eμ-myc driven mouse model, underlining the critical role of alternative splicing in cancer." (PMID 39313128, 2024). "Elevated PRMT5 expression is associated with poor clinical outcomes in cancer patients." (PMID 38791992, 2024). "Researchers believe that the vulnerability of PRMT5 in MTAP‐deficient cancers may extend both upstream of PRMT5 (methionine adenosyltransferase 2A, MAT2A) and downstream of PRMT5 (RIOK1 and other PRMT5 co‐complex members)." (PMID 39711357, 2024). "Endogenous inhibition of PRMT5 may also render MTAP-deficient cancers more sensitive to type I PRMT inhibition." (PMID 37237172, 2023). "In these MTAP-deficient cancer cells, inhibition of PRMT5 inhibits tumor growth." (PMID 37298093, 2023). "This suggests that MYC-dependent cancers may be susceptible to inhibitors of PRMT5 and other splicing regulators that may be overexpressed in MYC-driven cancer cells." (PMID 36979496, 2023). "Our analyses provide insights into the role of PRMT5 mutations in cancer cells." (PMID 37047013, 2023). "In line with this, overexpression of PRMT5 has been implicated in a number of cancer types." (PMID 37179124, 2023). "This study aims to dissect the mechanism underlying how PRMT5 is dysregulated in cancers." (PMID 37173967, 2023). "This PRMT5-dependent histone mark is a transcriptional repressor, suggesting that it may repress a subset of genes linked to proliferation and survival of cancer cells." (PMID 36230689, 2022). "Similar to PRMT7, PRMT4-, and PRMT5-regulated arginine methylation often co-occurred with phosphorylation and their methylation sites and sequences in the vicinity were vulnerable to cancer mutations." (PMID 33782401, 2021). "Protein arginine methyltransferase 5 (PRMT5) as an anti-cancer target has gained significant interest in recent years and high levels of PRMT5 protein are associated with worse survival outcomes across multiple cancer types." (PMID 34680285, 2021). "This evidence supports a model in which phosphorylation of PRMT5 may act as a pivotal step in enhancing the NF-κB response observed with PRMT5 overexpression which involves upregulation of the transcription of cancer-associated NF-κB target genes." (PMID 32456215, 2020). "Furthermore, it has been reported that upregulation of PRMT5 is closely associated with tumor progression and poor prognosis in several human cancers, including breast, gastric, colorectal, ovarian, leukemia, and lymphoma." (PMID 32759981, 2020).
cancer (continued). "Furthermore, an increase in its activity is associated with cell transformation, exposing PRMT5 as a suitable druggable target for treating cancer." (PMID 31139329, 2019). "One of the most recent studies linked PRMT5 to genetic variations in cancer cell tumorigenicity." (PMID 30922330, 2019). "The MTAP-deficient cancer cells are more sensitive to the PRMT5 inhibitor." (PMID 30283496, 2018). "Besides altering pro-survival and cell death pathways, PRMT5 has been implicated in reprogramming of lipogenesis in cancer cells, and in modulation of the G1 to S phase checkpoint under high glucose concentration." (PMID 30613353, 2018). "The arginine methyltransferase PRMT5 has been increasingly associated with cancer development." (PMID 29876520, 2018). "In light of these results, PRMT5 is able to promote cancer cell growth by causing global chromatin changes through methylation of promoter histones H3R8 and H4R3, as well as by modifying specific arginine residues of key transcription factors including E2F1 and NF-kB/p65." (PMID 30613353, 2018). "Consequently, cancer cells with MTAP deletion are highly susceptible to PRMT5 inhibition." (PMID 39885614, 2025). "Therefore, further analysis of the regulation of other oncogenic signals and cancer-associated transcription factors via PRMT5 induced by STAT3 should provide insights into the molecular mechanisms underlying the oncogenic functions associated with the PRMT5/STAT3 activation loop." (PMID 38760429, 2024). "Interestingly, spliceosome-mutated cancers may represent a synthetic lethal vulnerability to PRMT5-targeting therapies." (PMID 37861290, 2023). "In addition, dysregulation of PRMT5 is associated with multiple cancers and neurological disorders." (PMID 36572880, 2022). "Importantly, MTAP loss determines the accumulation of the MTA substrate, a natural inhibitor of protein arginine methyltransferase 5 (PRMT5), thus generating a hypomorphic PRMT5 state in MTAP‐deficient cancers that are, in this way, selectively sensitized to further PRMT5 inhibition." (PMID 32301278, 2020). "Moreover, we provide evidence showing that NAA40 depletion and loss of N-acH4 significantly reduce the global levels of the adjacent histone mark H4R3me2s through transcriptional repression of PRMT5 which in turn alters the expression of its own cancer-associated target genes." (PMID 30858358, 2019). "Furthermore, PRMT5 has recently been implicated in control of growth-promoting and pro-survival pathways, thereby demonstrating its versatile enzymatic roles in epigenetic regulation of anti-cancer target genes and organelle biogenesis." (PMID 31068219, 2019). "Our results define PRMT5-driven Top1 arginine methylation as a crucial regulatory mechanism and highlight PRMT5i as a means to potentiate Top1-based cancer treatment." (PMID 42216760, 2026). "In recent years, an increasing number of studies have demonstrated that PRMT5 inhibitors, already used in clinical trials can sensitize cancer cells to various therapeutics." (PMID 41513606, 2026). "Both PRMT5 and EphA2 proteins are overexpressed and play a crucial role in multiple cancers, and have been used as targets to develop new anticancer drugs." (PMID 41930341, 2026). "Strikingly, combining PRMT5 inhibitors (PRMT5i) with Top1 poisons such as irinotecan enhances cytotoxicity across multiple cancer cell types." (PMID 42216760, 2026). "In this review, we highlight the current understanding of PRMT5 biology in cancer, summarize preclinical studies supporting PRMT5 as a therapeutic target in ATLL, and discuss key challenges to future clinical translation." (PMID 41600858, 2026). "The broader relevance of PRMT5-mediated intron retention in other cancers, including neuroendocrine tumors, as well as its potential role in exon skipping, remains uncertain." (PMID 40846633, 2025).
cancer (continued). "For instance, large-scale RNA interference data from the Cancer Dependency Map (DepMap) and Project Drive led to the discovery of PRMT5 as a promising target in 9p21.3−/− cancers through its synthetic lethal interactions with MTAP deletion." (PMID 39910293, 2025). "Protein Arginine Methyltransferase 5 (PRMT5) is an epigenetic regulator currently undergoing clinical trials as a potential therapeutic target for cancer." (PMID 41226455, 2025). "Future research should investigate the broader network of proteins modulated by PRMT5 in both ferroptosis and cancer progression." (PMID 40756764, 2025). "The high expression of MAT2A and PRMT5 in cancer cells with a homozygous deletion of the MTAP gene appears to be a negative predictive factor of treatment with PRMT5 and MAT2A inhibitors." (PMID 41465382, 2025). "Protein Arginine Methyltransferase 5 (PRMT5) is an epigenetic regulator undergoing clinical trials as a potential therapeutic target for cancer." (PMID 40864819, 2025). "Currently, inhibitors targeting PRMT5 are actively being investigated as potential anti-cancer drugs." (PMID 41463372, 2025). "Regarding sensitivity to PRMT5 inhibitors, MTAP deletion renders cancer cells more susceptible to these inhibitors." (PMID 40264765, 2025). "Colony formation assays demonstrated that an acute knock out of PRMT1 or PRMT5 significantly increased the sensitivity levels of cancer cells to PARPi treatment, thereby phenocopying the results obtained using chemical PRMT inhibitors." (PMID 38826355, 2025). "PRMT5 thus appears to regulate splicing in cancer stem cells in a tissue-dependent manner, with BCSCs potentially reliant upon a higher fidelity of DNA repair transcript splicing to maintain genome stability, longevity, and chemoresistance compared to GSCs." (PMID 39695328, 2025). "The discovery of MTA-uncompetitive PRMT5 inhibitors has galvanized drug discovery efforts to generate precision cancer medicines since MTA is elevated in many cancers due to deletion of MTAP, thereby exposing a synthetic lethal vulnerability." (PMID 41339334, 2025). "The promising effects of PRMT5 inhibitors in targeted therapy of methylthioadenosine phosphorylase-deleted cancers are particularly highlighted." (PMID 39826691, 2025). "For example, the gain-of-function of PRMT5 has been demonstrated to contribute to cancer progression, with its regulatory influence extending to various signaling pathways." (PMID 40619438, 2025). "Consistently, “DNA-repair” was a significant signature that positively corrected with both PRMT1 and PRMT5 expression levels in cancer cell lines." (PMID 38826355, 2025). "Prior studies showed that type I PRMT and type II PRMT5 inhibitors are effective specifically in MTAP-deficient cells; yet, our data in MTAP-intact cancer cells show that targeting PRMT1 reduces persistence." (PMID 39699269, 2025). "PRMT5 has been shown to be overexpressed and negatively correlated with patient survival in many types of cancers." (PMID 41226455, 2025). "Our findings reveal a new way by which nucleus-localized TLR3 contributes to chemoresistance and poor prognosis of cancer via interactions with oncogenic PRMT5 and c-Myc in the nucleus." (PMID 40675966, 2025). "These inhibitors are under investigation for their ability to target and eliminate cancer cells, particularly those with specific genetic alterations that make them vulnerable to PRMT5 inhibition." (PMID 41463372, 2025). "PRMT5 has been observed to be upregulated in various cancer types and is known to regulate crucial tumorigenic events such as proliferation, EMT, invasion, and stem cell maintenance." (PMID 41150697, 2025). "The high MTA and low SAM environments diminish PRMT5 function and activity in MTAP-deficient cancers." (PMID 40430461, 2025). "PRMT5 dysregulation contributes to the pathogenesis of several diseases, including cancer, inflammation, and metabolic disorders." (PMID 40619438, 2025).